RN7SL787P (RNA, 7SL, cytoplasmic 787, pseudogene)
Gene: Miscellaneous RNA gene on chromosome 9 (67,791,499 to 67,791,782, reverse strand). Ensembl gene ENSG00000274098.
Homologues: Orthologues: chimpanzee Metazoa_SRP (99% identical), macaque Metazoa_SRP (94% identical). Paralogues in human: RN7SL544P (99% identical), RN7SL763P (99% identical), RN7SL565P (99% identical), RN7SL722P (99% identical), RN7SL52P (99% identical), RN7SL205P (97% identical), RN7SL1 (81% identical), RN7SL2 (81% identical), RN7SL3 (81% identical), RN7SL322P (80% identical), RN7SL230P (80% identical), RN7SL709P (80% identical), and 704 more.